CTLA4 (cytotoxic T-lymphocyte associated protein 4)
Diseases named in the same sentence as CTLA4 in open-access papers (continued):
Sharing a sentence is not in itself a finding about the gene and the disease.
tumor (continued). "Using an experimental model of Fc-receptor deficient mice, the anti-tumor effect of the anti-CTLA4 antibody was shown to be dependent on antibody-dependent cellular cytotoxicity of TI T-regs instead of re-activating conventional T-cells." (PMID 31547627, 2019). "In preclinical models, anti-CTLA-4 antibodies cause tumor rejection by engaging Fc receptors which are critical for antibody-dependent cell-mediated cytotoxicity (ADCC) or antibody-dependent cell-mediated phagocytosis (ADCP)." (PMID 31681327, 2019). "restored response to anti-CTLA-4 therapy associated with T-helper 1 (TH1) immune responses in tumor-draining lymph nodes and maturation of intratumoral dendritic cells (DCs)." (PMID 30887236, 2019). "STAT3 inhibition was shown to upregulate immune checkpoints such as cytotoxic T lymphocyte associated protein 4 (CTLA-4) and programmed cell death protein 1 (PD-1) to enhance anti-tumor immune responses." (PMID 31698775, 2019). "In fact, mice bearing melanoma tumors with knockdown of INF-γ receptor 1 have impaired tumor rejection upon anti-CTLA-4 treatment, illustrating that loss of the INF-γ signaling pathway is associated with primary resistance to checkpoint blockade." (PMID 35582274, 2019). "Density of tumor-infiltrating effector T cells has been previously associated with response to CTLA-4 and PD-1 inhibitors in SKCM; however, less is known about associations between B cells and immunotherapy response." (PMID 31138334, 2019). "Blockade of T cell co-inhibitory molecules such as CTLA-4 and PD-1 with monoclonal antibodies (mAb) (“immune checkpoint inhibitors”) to remove tumor-associated immune tolerance has been successful in clinical trials in cancer." (PMID 30788290, 2019). "Treatment of mice with (R)-crizotinib in combination with CDDP caused an increase in the mRNA levels of PD-1, PD-L1, and CTLA-4 within the tumor." (PMID 30940805, 2019). "Cancer cells exploit weaknesses in the natural regulation of T-cells by inducing the expression of co-inhibitory signals such as cytotoxic T-lymphocyte-associated protein 4 (CTLA-4) or programmed death ligand 1 (PD-L1) on tumor-infiltrating lymphocytes." (PMID 31366129, 2019). "Consistent with the role of Tregs in limiting tumor-associated inflammation, blockade of CTLA-4 signaling by antibody increased the expression of IL-17A in tumors." (PMID 31775909, 2019). "An increasing number of studies demonstrated that the suppression of immune response in tumor microenvironment is generally achieved by programmed death 1 (PD1) or cytotoxic T lymphocyte-associated protein 4 (CTLA4) on T cells." (PMID 31652645, 2019). "Interactions with cytotoxic T-lymphocyte associated antigen 4 (CTLA-4) receptor or the programmed cell death protein 1 receptor (PD-1) or ligand (PD-L1) negatively regulate T-cell activation and enable tumor evasion from immune detection." (PMID 31053161, 2019). "Knockdown of both IFN receptors on tumor cells considerably improved the response to the combination of radiotherapy with anti-CTLA-4 mAb through specific down regulation of genes associated with acquired resistance." (PMID 31481761, 2019). "PD-1 and cytotoxic T lymphocyte-associated protein 4 (CTLA-4) are negative regulators of T cells that promote T cell anergy in the tumor microenvironment." (PMID 31889898, 2019). "Antibodies directed against PD-1, its ligand (PD-L1), and CTLA-4 have demonstrated remarkable efficacy in tumor types with a high mutational burden." (PMID 30654522, 2019). "In contrast to CTLA-4, PD-1 blockade is thought to act primarily within the tumor microenvironment and has been associated with fewer and less severe irAEs in the clinic." (PMID 30936880, 2019). "Immune checkpoints such as CTLA-4 (cytotoxic T lymphocyte-associated antigen-4) and PD-1 (programmed cell death protein 1), which regulate the activation of lymphocytes and balance immune responses, can protect tumor cells from the immune response." (PMID 31137573, 2019).
tumor (continued). "An increased ratio of CTL to Treg in tumor tissues has been associated with response to CTLA-4 and PD-1 blockade." (PMID 31555274, 2019). "Therapies targeting the programmed cell death-1 (PD-1), programmed cell death ligand-1 (PD-L1) and cytotoxic T-lymphocyte-associated antigen-4 (CTLA-4) immune checkpoints have received approval across a wide range of tumor types, including NSCLC." (PMID 31871778, 2019). "Expression of CTLA-4, PD-1 and Tim-3 molecules was associated with T-cell exhaustion in chronic viral infections and tumour progression." (PMID 31350404, 2019). "The developers of the inhibitory anti-CTLA-4 antibody started with the premise that a CTLA-4 (cytotoxic T lymphocyte-associated antigen 4) blockade would selectively target anti-tumor T cells." (PMID 31046789, 2019). "Because both CTLA-4 and PD-1 are expressed mainly on lymphocytes, several reports have pointed out the association between blood lymphocyte count and tumor response to ICIs." (PMID 31192215, 2019). "Its significance in anti-tumor immunity was described over 20 years ago in murine models where blockade of CTLA-4 caused tumor rejection both in established tumors and with secondary exposure to tumor cells." (PMID 31877721, 2019). "Treg-specific CTLA-4 deficiency was shown to affect in vivo Treg suppressive function and promote tumor immunity." (PMID 29843754, 2018). "Current immunotherapies focus on suppressing tumor cell evasion using antibodies that inhibit immune checkpoint molecules, including cytotoxic T-lymphocyte-associated antigen 4 (CTLA-4), programmed death 1 (PD-1), and programmed death-ligand 1 (PD-L1)." (PMID 30227629, 2018). "Type I immune responses, which include IFN-γ production and cytotoxic T cell functions, are important for effective anti-tumor immune responses and are associated with better responses to anti-CTLA-4 and anti-PD-1 treatments." (PMID 29644214, 2018). "Here, we summarize recent studies investigating the PD-L1 expression or mutational load of tumor tissues as well as the frequency and phenotype of immune cells in tumor patients prior to and during CTLA-4 or PD-1/PD-L1 inhibitor treatment." (PMID 29494517, 2018). "The inflammation made the tumor tissues susceptible to systemic CTLA-4 blockade therapy, leading to tumor rejection and resulted in increased survival rate in the mice treated with the combined therapy." (PMID 29857493, 2018). "In general, anti-CTLA-4 check-point blockade has been associated with greater tumor entry, although the exact mechanism for this increase in tumor entry has yet to be determined." (PMID 30542345, 2018). "A special population of CD8 positive T cells have been identified as “partially exhausted” cytotoxic T lymphocytes (peCTL), which are tumor-infiltrating CD8+ T cells which express high levels of cytotoxic T lymphocyte–associated antigen 4 (CTLA-4)." (PMID 29368638, 2018). "The tumor progression in wild-type samples was associated with upregulation of immunoinhibitory genes, including PD-1, CTLA-4, TIM3, and LAG3." (PMID 29296022, 2018). "Tumor foreignness: for example, it is reported that the outcome to anti-CTLA-4 blockade therapy correlates with increased tumor mutational burden (a measure of neoantigen load)." (PMID 30200478, 2018). "Preclinical studies in mice have shown that optimal anti-tumor activity of anti-CTLA-4 antagonist antibodies required co-engagement of FcγRs expressed by tumor-associated effector cells to selectively deplete CTLA-4-expressing intratumoral Treg cells." (PMID 29617360, 2018). "Tumor specific activated T cells as well as regulatory T cells express cytotoxic T lymphocyte-associated antigen 4 (CTLA-4), which binds to CD80/CD86 on antigen presenting cells and leads to T cell anergy by competing with CD28 as a costimulatory molecule." (PMID 30101129, 2018).
tumor (continued). "Recent studies have shown that an elevated tumor mutational load or predicted class-I neoantigen content is associated with higher response rate and survival to PD-1 or CTLA-4 blockade in melanoma." (PMID 30097571, 2018). "In keeping with this, IgG1SDALIE mAb, with an optimized A:I (CD16:CD32b) binding profile, demonstrated superior anti-tumor activity relative to all evaluated chimeric anti-CTLA-4 Fc variants." (PMID 29576375, 2018). "CTLA-4 blockade was associated with increased IFNγ-producing tumor-infiltrating T cells and extended survival of dexamethasone-treated mice." (PMID 29891009, 2018). "An increased ratio of CTL compared with Treg in tumor tissue has been associated with response to CTLA-4 and PD-1 blockade." (PMID 29970158, 2018). "In vivo combination treatment with pemetrexed and sildenafil enhanced the anti-tumour efficacy of checkpoint inhibitory antibodies directed against programmed cell death protein 1 (PD-1) or cytotoxic T-lymphocyte-associated protein 4 (CTLA4)." (PMID 29743944, 2018). "Treg cells can secrete cytotoxic T-lymphocyte-associated antigen 4 (CTLA-4), PD-1, and other immunosuppressive molecules and promote tumor escape by inhibiting the proliferation and activation of effector T cells." (PMID 29849718, 2018). "Anti-CTLA-4 mAbs with the same Fc variants employed in ipilimumab (IgG1) and tremelimumab (IgG2) both induced in vivo depletion of tumor-infiltrating Treg cells in the context of human FcγRs." (PMID 29576375, 2018). "Using whole-exome sequencing to examine non-small-cell lung cancer (NSCLC) treated with PD-1 plus CTLA-4 blockade, we found that high tumor mutation burden (TMB) predicted improved objective response, durable benefit, and progression-free survival." (PMID 29657128, 2018). "Diverse metrics of tumor immune infiltration including the amount of CD8+ cytotoxic T-cells or RNA signatures of T-effector cells have been linked with clinical benefit to CTLA-4 and PD-1 axis blockers." (PMID 30097571, 2018). "Targeting of tumor-associated macrophages with anti-CSF-1R reduced their infiltration, and when used in combination with anti-PD-1 or anti-CTLA-4, enhanced tumor regression." (PMID 29968076, 2018). "In this context, T-cell pathways that are associated with regulatory checkpoints, such as PD-1 and CTLA-4, are inhibited to augment anti-tumour responses." (PMID 30631436, 2018). "Among these immune checkpoints, cytotoxic T-lymphocyte-associated antigen (CTLA)-4 and Tim-3 appeared to be associated with tumor antigen-specific CD8+ T-cell dysfunction in melanoma patients." (PMID 30158938, 2018). "Effectiveness of these therapies will depend on their ability to target potent tumor-specific or tumor-associated antigens, overcome the mechanisms of immune tolerance, and nullify immunosuppressive pathways (e.g. PD-1/L1, CTLA-4, etc.)." (PMID 29751789, 2018). "In HNSCC, high levels of TAM were found in tumor microenvironment and were associated with CTLA-4-related immunosuppression, the expression of PD-L1 and immunosuppressive cytokines, as well as metastasis and poor prognosis." (PMID 29976244, 2018). "Of interest, a joint clinical and preclinical study in patients with metastatic melanoma implicated T-cell exhaustion from upregulation of tumor PD-L1 expression in the resistance towards treatment with radiation and CTLA-4 antibody." (PMID 30558196, 2018). "We showed that these epitopes render mice bearing progressively growing tumours susceptible to tumour rejection following treatment with anti-CTLA-4 and/or anti-PD-1." (PMID 28916749, 2017). "Durable clinical responses to the CTLA-4 blockade were recently correlated with tumor mutational load and the expression of antigenic tetra-peptides that resembled those found in viral and bacterial pathogens." (PMID 28405494, 2017).
tumor (continued). "During treatments of immune checkpoint inhibitors such as antibodies against PD-1 or cytotoxic T lymphocyte-associated antigen-4 (CTLA-4), tumor responses were observed and assessed using Response Evaluation Criteria in Solid Tumors (RECIST)." (PMID 28915720, 2017). "Molecules related to tumor escape from T-cell attack include cytotoxic T lymphocyte-associated protein-4 (CTLA-4) and programmed death-1 (PD-1), which are upregulated on T cells as a counter-regulatory mechanism upon prolonged stimulation." (PMID 27966460, 2017). "Checkpoint inhibitors such as nivolumab or pembrolizumab (programmed cell death 1 or PD-1 inhibitors) and ipilimumab (a cytotoxic T-lymphocyte-associated protein 4 or CTLA-4 inhibitor) enhance the immune response to a tumor." (PMID 28730140, 2017). "Based on these data, we wanted to evaluate the efficacy of blocking PD-L1 or CTLA-4 in combination with loss of the intracellular checkpoint Cbl-b in a murine tumor model." (PMID 28611299, 2017). "In metastatic lymph nodes, high expression of CTLA-4 in tumor epithelial cells was associated with an adverse DSS (HR 1.65 95% CI 1.03–2.65, P = 0.037)." (PMID 28707078, 2017). "James Alison’s group was the first to demonstrate that the blockade of the CTLA-4 signal by a monoclonal antibody (mAb) alone can cause tumor regression in a transplanted mouse tumor model." (PMID 29211042, 2017). "The presence of neoantigens derived from tumor mutations was investigated in three studies of CTLA-4 ICI." (PMID 29034210, 2017). "Each of these antibodies targets an IgV-domain containing immune receptor expressed by activated T cells (PD-1 and CTLA-4), or tumor or tumor-associated myeloid cells (PD-L1), that functions to inhibit antigen-dependent T cell responses." (PMID 29230210, 2017). "CTLA-4 expression on tumor cells was associated with a bad prognosis while good outcomes were observed when CTLA-4+ TIL were present." (PMID 29163490, 2017). "For example, CTLA4 is known to be expressed by T reg cells and activated T cells to prevent further T cell activation and thereby causing inhibition of the anti-tumor immune response." (PMID 28174608, 2017). "The association study showed that the expression of CTLA-4 in the tumor was significantly associated with the UICC stage." (PMID 26918337, 2016). "Tumor-associated CTLA-4 has been shown to inhibit anti-tumor T cell immunity by interacting with CD28 expressed on T cells to induce tumor-specific T cell apoptosis or by impairing cytokine production and T cell-mediated cytotoxicity." (PMID 27050369, 2016). "For example, in BRCA1-deficient ovarian cancer, inhibition of poly(ADP-ribose) polymerases (PARPs), a family of enzymes involved in DNA repair, markedly increases mutational load in tumor cells and has demonstrated synergistic potential with CTLA-4 blockade." (PMID 27959922, 2016). "In particular, immune checkpoint blockade therapies with anti-CTLA-4 and anti-PD-1/PD-L1 are causing dramatic tumor shrinkage and prolonged patient survival in a variety of cancers." (PMID 27660710, 2016). "In the RM-1 prostate cancer model, a 4-1BBL-expressing tumor cell vaccine combined with CTLA-4 blockade caused tumor rejection in four out of five mice implanted with RM-1 tumors." (PMID 27034234, 2016). "The PD-1 (programmed cell death protein 1) and CTLA-4 (cytotoxic lymphocyte-associated antigen 4) immune checkpoint pathways can both contribute to tumour immune evasion." (PMID 26918344, 2016). "Tumor regression was correlated with CD8+/Treg ratio suggesting a potential synergistic role of the association of anti-CTLA-4 with the Treg depleting therapies." (PMID 27447625, 2016). "Several reports show that combinations of ACT and blockade of inhibitory molecules, such as CTL-associated antigen 4 (CTLA-4) and PD-1, have the potency to augment anti-tumor efficacy and increase T cell persistence." (PMID 27656185, 2016).
tumor (continued). "Under normal circumstances, the PD-l/PD-L1 and CTLA-4/B7 checkpoint pathways prevent aberrantly activated T cells from causing autoimmunity; therefore, expression of these ligands by tumor cells allows circumvention of the immune system." (PMID 27766079, 2016). "CTLA4 is an immune checkpoint receptor and up-regulation of the CTLA4 pathway leads to suppression of antitumor immunity, which is consistent with the immunosuppression feature found in tumor-associated or tumor-induced inflammation." (PMID 28027300, 2016). "The mismatch repair–deficient tumor microenvironment strongly expressed several immune checkpoint ligands, including PD-1, PD-L1, CTLA-4, LAG-3 and IDO, to protect the tumor cells from death." (PMID 26967246, 2016). "In univariate analyses (log-rank), higher interstitial CTLA-4+ lymphocyte density and higher tumor CTLA-4 expression were associated with shorter overall survival (OS)." (PMID 27050369, 2016). "CTLA-4 expression was noted in OS cell lines and patient tumor samples and CTLA-4 + 49G/A polymorphism was associated with increased risk of developing OS." (PMID 26286851, 2015). "The administration of GM-CSF–secreting tumor cell vaccines combined with anti-CTLA-4 has been associated with an increased ratio of intratumoral CD8+ T lymphocytes to Tregs." (PMID 26143264, 2015). "Expression of specific ligands, such as PD-L1 and CTLA-4, in the stroma or in the tumor cells associated, is paramount to improve growth and resistance to immune attack." (PMID 26236750, 2015). "Antibodies against CTLA-4, PD-1, and its corresponding ligand PD-L1 aim to reactivate tumor-specific T cells and cause a robust anti-tumor immune response." (PMID 27066495, 2015). "The anti-tumor effects associated with blocking CTLA4 in vivo have been shown to involve depletion of regulatory T cells as well as restoring effector T cell function." (PMID 25614821, 2015). "Other strategies have focused on increased DC function by cotransfecting tumor antigen mRNA with mRNA encoding for checkpoint molecules such as CTLA-4 and GITR." (PMID 26665011, 2015). "Ipilimumab is a fully human monoclonal antibody that promotes anti-tumor T Cells by blocking cytotoxic T-lymphocyte-associated antigen 4 (CTLA-4), an immune checkpoint molecule that down-regulates pathways of T-cell activation." (PMID 25164960, 2015). "In a pilot study conducted in 15 patients treated with anti-CTLA-4 Tremelimumab, the clinical response was also associated with an increase in tumor infiltration by CD8+ TIL and a variable association with CD4+ TIL." (PMID 24741578, 2014). "A recent preclinical study showed that low dose anti-CTLA-4 delivered i.t. caused a reduction in tumor-associated Tregs and regression of a distal tumor." (PMID 25518732, 2014). "When used in conjunction with anti-CTLA-4 antibodies, RT has been associated with an immune-mediated inhibition of tumor cells outside the irradiated field—also known as the abscopal effect." (PMID 25268164, 2014). "CTLA-4 blockade in murine cancer models increased the regression of immunogenic tumors, but caused depigmentation, thus implying a role for CTLA-4 not only in tumor antigenicity, but also in the suppression of autoimmunity." (PMID 24594636, 2014). "Comparing the results of CTLA-4 SNP genotyping in the tumor tissue and the corresponding blood sample, a shift from one genotype to another in more than 60% of patients was observed, for both studied CTLA-4 polymorphisms." (PMID 23936819, 2013). "We anticipated that the chemotherapy would cause tumor shrinkage and immunogenic antigen release while the anti-CTLA-4 would enhance T cell activation and expansion." (PMID 23626745, 2013). "In preclinical studies with knockout mice it has been reported that CTLA-4 deficiency in CD4+CD25+ Treg impairs its suppressive function in tumor immunity." (PMID 23861693, 2013).